CIAPIN1 (cytokine induced apoptosis inhibitor 1)
Diseases named in the same sentence as CIAPIN1 in open-access papers (continued):
Sharing a sentence is not in itself a finding about the gene and the disease.
cancer (12 papers, 2010 to 2024). A tumor composed of atypical neoplastic, often pleomorphic cells that invade other tissues. "Obviously, CIAPIN1 has been expressed in various tissues, and several reports showed that the expression of CIAPIN1 protein in tumor tissue is associated with cancer prognosis." (PMID 34201138, 2021). "Further experiments are needed to validate possible multifunctional roles of CIAPIN1 in cancer, more CCA cell lines, and also other tumor cell lines should be used to explore the biological function of CIAPIN1 in various cancers." (PMID 35807116, 2022). "CIAPIN1 was reported as a candidate indicator for diagnosis and prognosis for several human cancers and is proposed as a therapeutic target for anticancer interventions." (PMID 34201138, 2021). "CIAPIN1 overexpression has also been shown to confer resistance to cancer treatment, therefore predicting a worse patient prognosis and survival." (PMID 31645899, 2019). "The expression of cytokine-induced apoptosis inhibitor 1 (CIAPIN1) correlates with the malignant progression of several cancers." (PMID 22713669, 2012). "Positive nuclear expression of CIAPIN1 positively correlated with the degree of differentiation, indicating that the CIAPIN1 nuclear expression in poorly differentiated cancer was significantly higher than that in well-differentiated cancer (P < 0.0001)." (PMID 22713669, 2012). "The relationship between CIAPIN1 expression and patients' characteristics (gender, age, location of cancer, UICC stage, local recurrence and tumour grade factors) was evaluated." (PMID 20815902, 2010). "Results indicated that CIAPIN1 was mainly expressed in the cytoplasm and nucleus, and that its expression level in cancer samples was significantly lower than in normal tissues." (PMID 20815902, 2010). "The correlation between expression level of CIAPIN1 and patients' characteristics, such as gender, age, location of cancer, UICC stage, local recurrence and tumour stage factors was investigated." (PMID 20815902, 2010). "Based on these results, we confirmed that CIAPIN1 protein expression was lower in carcinomas tissues compared with adjacent normal tissues." (PMID 20815902, 2010). "To elucidate whether CIAPIN1 can be a molecular target for cancer chemotherapy, we predicted the networks of CIAPIN1 and related proteins in the signaling pathway and chemotherapeutic drugs using STITCH." (PMID 35807116, 2022). "CIAPIN1 is Ras signalling mediator and plays multiple roles in cancer development." (PMID 32672400, 2020). "Cytokine-induced apoptosis inhibitor 1 (CIAPIN1) acts as a downstream effector of the receptor tyrosine kinase-Ras signaling pathway and has been reported as a candidate tumor suppressor gene in various cancers." (PMID 31093311, 2019). "The distinguishable role of CIAPIN1 might be due to the tumor types, indicating that CIAPIN1 exerted variable roles in different cancers." (PMID 31093311, 2019). "Current study has revealed that CIAPIN1 may have wide and important functions, especially due to its close correlations with malignant tumors." (PMID 22717413, 2012). "Therefore, improved knowledge of the subcellular localization of CIAPIN1 in tumors will be instrumental for the design of optimal strategies to selectively disrupt CIAPIN1 in human cancers." (PMID 22713669, 2012). "Thus, CIAPIN1 might have a contrary function among different cancers or even within CCA via different signal pathways." (PMID 35807116, 2022). "Hence, CIAPIN1 might play a role in cancer drug resistance and be a molecular target for cancer chemotherapy." (PMID 35807116, 2022). "Thus, CIAPIN1 might be likely involved in important physiological functions in cancer." (PMID 31093311, 2019). "Taken together, our results revealed that CIAPIN1 was differentially expressed in normal adjacent tissues and cancer tissues from the same CRC patient and that CIAPIN1 expression was closely related to the tumour state, local recurrence and UICC stage." (PMID 20815902, 2010).
cancer (continued). "Some previous studies reported that CIAPIN1 could affect the cell proliferation and cell cycle progression and it may be involved in regulating MDR in some cancers." (PMID 22717413, 2012). "The role of CIAPIN1 in cancer progression and metastasis is not yet defined." (PMID 31645899, 2019). "We hypothesize that nuclear CIAPIN1 expression may be involved in neoplastic alterations, while the function of the cytoplasmic protein does not contribute to cancer progression." (PMID 22713669, 2012).
tumor (12 papers, 2010 to 2025). "Our laboratory also indicated a direct correlation between the loss of CIAPIN1 and the proliferation of tumours in human digestive cancer." (PMID 20815902, 2010). "Although the expression level of CIAPIN1 has been found to relate to an oncogene or tumor suppressor in many different solid tumors, its expression, biological roles, and its mechanism in CCA have not been investigated." (PMID 35807116, 2022). "In oncogenesis research, the overexpression of CIAPIN1 has been reported in various solid tumors and is considered an oncogene or tumor suppressor in different tumor types." (PMID 35807116, 2022). "This study aimed to examine the expression of CIAPIN1 in CCA tumor tissue specimens and evaluate its prognostic value." (PMID 35807116, 2022). "The mean tumor size of scramble cells at 36 days was 1017 mm3, whereas the mean tumor sizes of A549 cells with CIAPIN1 overexpression were 667 mm3." (PMID 31093311, 2019). "By univariable and multivariate analysis, we found that tumor size, depth of invasion, and CIAPIN1 expression are the independent prognostic factors for OS, while tumor size and depth of invasion are the independent prognostic factors for DFS." (PMID 31093311, 2019). "Of note, A549 cells engineered to overexpress CIAPIN1 showed a marked decrease in the onset of the first palpable tumor." (PMID 31093311, 2019). "In another study carried out in GC cells, CIAPIN1 silencing inhibited cell proliferation and angiogenesis, suggesting that this gene is important for initiation of tumor vascularization." (PMID 31645899, 2019). "It was clear that the tumor tissue specimens had a decrease trend of CIAPIN1 expression as compared with the normal lung tissue, which was consistent with the level of CIAPIN1 protein expression determined by immunohistochemical staining." (PMID 31093311, 2019). "CIAPIN1 protein expression correlated with having a primary tumour (pT), tumour stage (UICC), and histological grade (P = 0.0393, 0.0297, and 0.0397, respectively)." (PMID 20815902, 2010). "In the present study, using a combination of gene silencing and mass spectrometry techniques followed by bioinformatic analysis revealed that CIAPIN1 and related proteins are involved in calcium signaling and adherens junction pathways, both of which are related to tumor metastasis." (PMID 35807116, 2022). "Taken together, we speculate that, via NOS1, CIAPIN1 activates the TGF-β/SMADs signaling pathway to augment tumor metastasis." (PMID 35807116, 2022). "Moreover, STITCH analysis combined with KEGG signaling pathway search revealed that, via NOS1, CIAPIN1 interacted with nine proteins related to cell migration, invasion, and metastasis of tumor cells." (PMID 35807116, 2022). "In terms of CIAPIN1 and tumor metastasis, there are some research papers mentioning on this issue." (PMID 34201138, 2021). "In the SGC7901 and MKN45 GC cell lines, it was shown that reduction in CIAPIN1 expression promoted tumor growth, suggesting that CIAPIN1 may act as a suppressor of GC cell proliferation." (PMID 31645899, 2019). "Furthermore, CIAPIN1 was found to be ubiquitously distributed in both normal fetal and tumor tissues, with high expression in actively metabolic tissues." (PMID 31093311, 2019). "Moreover, A549 cells with CIAPIN1 overexpression showed a significant decrease in tumor outgrowth after injection when compared with control cells." (PMID 31093311, 2019). "Remarkably, the involvement of CIAPIN1 in tumor metastasis mechanisms is still unknown." (PMID 35807116, 2022). "Therefore, a possible explanation for the results obtained in the present study is that CIAPIN1 may be recruited by MYC to maintain the angiogenesis required for tumor progression." (PMID 31645899, 2019). "Thus, we hypothesize that CIAPIN1 might exert inhibitory function in tumor biological behavior such as metastasis of NSCLC cells." (PMID 31093311, 2019).
tumor (continued). "Furthermore, stable transfection of CIAPIN1 siRNA may contribute to carcinogenesis by accelerating cell proliferation and promoting cell-cycle progression in vitro and in vivo in the two tumour types." (PMID 20815902, 2010). "In the present study, we investigated the expression of CIAPIN1 in human CCA tissues and CCA cell lines to elucidate the role of CIAPIN1 and its molecular mechanisms in CCA tumorigenesis/tumor progression." (PMID 35807116, 2022). "We found that the CIAPIN1 expression level was inversely correlated with histological type, TNM stage, tumor size, and depth of invasion." (PMID 31093311, 2019). "The Wilcoxon-Mann-Whitney test showed a significant difference in the differential expression of CIAPIN1 in patients with different T and UICC stages, and tumour grade (P = 0.0393, 0.0297 and 0.0397, respectively)." (PMID 20815902, 2010). "Although the regulatory mechanism of CIAPIN1 in CRC was still unclear, our studies had provided evidence that CIAPIN1 expression correlated with the differentiation level and prognosis of CRC, suggesting it was an important role in tumour biology." (PMID 20815902, 2010). "CIAPIN1-positive expression in CRC was 47.25% (129/273), significantly lower than 79.85% (218/273) in the unaffected tissue adjacent to the tumour (P <0.01)." (PMID 20815902, 2010). "In addition, epithelial-to-mesenchymal transition (EMT) is critical for tumor metastasis and some EMT symbol markers were detected in A549 cells with CIAPIN1 overexpression." (PMID 31093311, 2019). "In addition, epithelial-to-mesenchymal transition (EMT) is critical for tumor metastasis and some EMT-specific markers were detected in A549 cells with CIAPIN1 overexpression." (PMID 31093311, 2019). "CIAPIN1 has been demonstrated to be ubiquitously distributed in normal fetal and tumor tissues, with high expression in actively metabolic tissues." (PMID 22713669, 2012). "In the previous study, we observed the distribution of the CIAPIN1 in a variety of cultured cell lines, including mouse fibroblast cell line NIH3T3, human tumor cell lines and immortalized cell lines by using immunofluorescence staining, immunohistochemistry and EGFP-CIAPIN1 fusion protein." (PMID 20815902, 2010). "Although the exact source of serum CIAPIN1 proteins remains unknown, higher serum CIAPIN1 levels of CCA patients might be attributed, at least in part, to CCA cells in tissues because CIAPIN1 was significantly expressed in CCA tumor compared with normal tissues." (PMID 34201138, 2021). "Conversely, the TreeSHAP model considered CIAPIN1 to be a non-contributory gene and instead highlighted APOBEC3D, which is known to drive tumor resistance." (PMID 41020875, 2025).
hematological disease (2 papers, 2012 to 2022). "CIAPIN1 has been reported to be involved in proliferation, multidrug resistance, angiopoiesis and anti-apoptosis in many solid tumors and hematological malignancies." (PMID 22713669, 2012).
CIAPIN1 also shares sentences with these, for which no sentence is quoted: pancreatic cancer (4 papers); cholangiocarcinoma (2); diffuse large B-cell lymphoma (2); esophageal squamous cell carcinoma (2); leukaemia (2); liver cancer (2); renal carcinoma (2); celiac disease (1); chronic myeloid leukemia (1); colon carcinoma (1); esophageal cancer (1); gastrointestinal disease (1); infection (1); ischemic stroke (1); large cell lung carcinoma (1); ovarian serous carcinoma (1); small cell lung carcinoma (1); squamous cell lung carcinoma (1); viral infections (1).